TEX13C (TEX13 family member C)
Gene: Protein-coding gene on chromosome X (125,319,871 to 125,325,216, forward strand). Ensembl gene ENSG00000282815.
Subcellular location (Human Protein Atlas): Plasma membrane; Nucleoplasm
Homologues: Orthologues: macaque TEX13C (78% identical), dog TEX13D (33% identical), rat Tex13c (24% identical), mouse Tex13c1 (23% identical), rat LOC134484021 (21% identical), mouse Tex13d (21% identical), Drosophila melanogaster CG14718 (6% identical). Paralogues in human: TEX13D (35% identical), TEX13A (10% identical), TEX13B (8% identical).